ENSG00000273155 (novel LIPT1-MRPL30 readthrough)
Gene: Protein-coding gene on chromosome 2 (99,154,998 to 99,195,298, forward strand). Ensembl gene ENSG00000273155.
Genetic constraint (gnomAD): Loss-of-function variants: 10 observed, 14.65 expected, observed/expected ratio (o/e) 0.68, 90% interval 0.42 to 1.16. Missense variants: 123 observed, 141.74 expected, observed/expected ratio (o/e) 0.87, 90% interval 0.75 to 1.01. Synonymous variants: 49 observed, 44.02 expected, observed/expected ratio (o/e) 1.11, 90% interval 0.88 to 1.41.